LRP1 (LDL receptor related protein 1)
Diseases named in the same sentence as LRP1 in open-access papers (continued):
Sharing a sentence is not in itself a finding about the gene and the disease.
tumor (continued). "The serpin E2/uPA covalent complex is decomposed after binding to low-density lipoprotein receptor-related protein 1 (LRP-1), stimulating ERK activation, promoting MMP9 expression, and aggravating tumor metastasis." (PMID 38469181, 2024). "Beyond its prognostic significance, LRP1 emerges as a key regulator of the TME, influencing immune cell infiltration and immune checkpoint pathways, thereby facilitating tumour immune evasion and progression." (PMID 39063239, 2024). "Further, our results identified potential ligand-receptor pairs (MDK/LRP1, MDK/ALK, GAS6/MERTK, and GAS6/AXL) for cell communication between these two types of cells and tumor cells." (PMID 37733241, 2023). "Interactions of tumor cells with the BM microenvironment involve preferred communication with myeloid cells through the MIF/CD44/CD74/CXCR4 and MK/LRP1/NCL axes." (PMID 37365178, 2023). "Collectively, our findings indicated that CAF-derived PAI-1 induces EndoMT in LECs by activating the LRP1/ERK1/2/AKT pathway, which in turn drives abnormal lymphangiogenesis, thereby facilitating tumour lymphoinvasion and CSCC progression." (PMID 37415190, 2023). "In particular, the interaction between Midkine (MDK, secreted by tumor cells) and a number of MDK-receptors (ITGA4, ITGA6, ITGB1, NCL, LRP1) on CD8+ T cells appears to be a recurrent immunosuppressive pathway seen across all three patients." (PMID 36973261, 2023). "It is suggested that degranulation of mast cells initiated via the PAI-1/LRP1/STAT3 axis leads to release of additional chemokines that trigger tumor infiltration of other immune cells and tumor progression." (PMID 38275375, 2023). "Blockade of PAI-1 or inhibition of LRP1/AKT/ERK1/2 abrogated EndoMT and consequently attenuated CAF-induced tumour neolymphangiogenesis." (PMID 37415190, 2023). "Hsp90AA1 promotes tumor aggressiveness and chemoresistance by activating AKT through LRP-1 (Low-density lipoprotein Receptor-related Protein 1)." (PMID 37835519, 2023). "Restoring LRP1 and tPA in the less aggressive, poorly metastatic B16F1 tumor cells enhanced tumor cell proliferation and led to massive lung metastasis in murine tumor models." (PMID 36612285, 2022). "The lipoprotein receptor-related protein 1 (LRP-1) inhibitors (ANG1005 and GRN1005) bind to LRP-1, leading to LRP-1 receptor-mediated transcytosis or endocytosis across the BBB, resulting in tumor growth arrest and apoptosis." (PMID 36232989, 2022). "CRT that is exposed on the surface of tumor cells experiencing ICD is an important “eat me” signal to promote tumor cell phagocytosis and antigen presentation via CD91, also known as LDL-receptor-related protein 1 (LRP1)." (PMID 36145510, 2022). "A large endocytic receptor LRP-1 mediated internalization of CD44, which plays an important role in the adhesive properties of tumor cells." (PMID 35024436, 2022). "Low-density lipoprotein receptor-related protein-1 (LRP-1) is widely expressed in a wide variety of tissues; it exhibits functionalities in supporting tumor cell proliferation by promoting the entry of the cell cycle into the S phase and decreasing apoptosis." (PMID 36106114, 2022). "We have previously reported that ablation of the low-density lipoprotein receptor-related protein 1 (LRP-1) completely nullified the ability of tumour cells to migrate and invade under serum-free conditions in vitro and to form tumours in vivo." (PMID 35835845, 2022). "Together with VLDLR and LRP1, LRP8 is also involved in tumor cell growth through its binding to the glycoprotein Proprotein convertase subtilisin/kexin type 9 (PCSK9)." (PMID 36012187, 2022). "Sodium selenite treatment upregulated pro-apoptotic, apoptotic, and tumor suppressor genes such as ATF3, FOSB, GADD45B, DUSP8 and ACHE, and downregulated tumor cell survival genes such as SCD, LRP1, RAB31, SRPX2, PDK1 and CSGALNACT1." (PMID 36059619, 2022).
tumor (continued). "While fibroblast cells, like tumor cells, expressed EGFR and FGFR1, they also exclusively expressed higher levels of the receptors LRP1, PDGFRs, and PLXND1 in both patients." (PMID 34459128, 2021). "Further functional studies based on in vitro tumor conditioned media (TCM) effects on human umbilical vein endothelial cells’ (HUVECs) behaviors and angiogenic capabilities reinforced LRP-1’s role in modulating the angiogenesis process." (PMID 34680548, 2021). "Several genes from the candidate gene-set with higher expression associated with higher 25-OHD are included in enriched GO ontology terms relevant to carcinogenesis and have reported tumour suppressor activity (e.g. FOXOs, CAV1, LRP1)." (PMID 34340708, 2021). "The patients with high KDR, PDGFRA, LRP1, COL1A2, and SAMD9 expression had shorter OS (log-rank test, P < 0.05), indicating that tumor antigens were critical for the progression of diffuse gliomas." (PMID 34815785, 2021). "It therefore seems critical to consider the LRP-1 expression level to refine clinical designs using TKI, especially because LRP-1 depletion is found in invasive tumour areas that are the most refractory to treatments." (PMID 34831480, 2021). "This study aimed to clarify LRP-1’s role in TNBC tumor growth, and more precisely its involvement in tumor angiogenesis using an MDA-MB-231 cell line-based model." (PMID 34680548, 2021). "exHSP90 (gp96) has been shown to bind to surface receptor CD91 (low-density lipoprotein receptor-related protein 1 (LRP1)) for promoting wound healing and tumor cell invasion." (PMID 33023034, 2020). "In contrast, during metastasis development, we supposed that LRP-1 expression is down-regulated after cleavage by sheddases leading to a higher expression of DDR1 at the cell surface and then an increased tumor invasion." (PMID 32582700, 2020). "Another strategy of tumor targeting was used with the NT4 peptide, a tetrabranched peptide from the human neurotensin, capable of binding LRP1 and LRP6 by mimicking ApoE and midkine heparin binding site." (PMID 32850302, 2020). "Our data demonstrate for the first time that LRP-1 can induce endocytosis of DDR1 in CRC, thus decreasing the ability of the 3D collagen matrix/DDR1 axis to inhibit tumor cell proliferation." (PMID 32582700, 2020). "Increased phagocytosis of tumor cells mediated by targeting CD47 was inhibited by CALR blockade and its interaction with low density lipoprotein receptor-related protein-1 (LRP1)." (PMID 28815041, 2017). "LRP1 regulates uPAR signaling via factors such as ERK-1/2, which promotes tumor cell survival, proliferation, migration and invasion." (PMID 29138479, 2017). "This study reports an interaction between a classical CXC chemokine receptor and LRP1, and shows a regulatory role of LRP1 in GPCR conformation, trafficking, and biological activity in tumor cells." (PMID 29146996, 2017). "On the other hand, miR-4510 treatment led to an increase in several important regulators of β-catenin functions and tumor suppressors such as AXIN2, E-cadherin (CDH1), LRP1 and WNT5A." (PMID 28476031, 2017). "This idea came from our previous reports that secreted Hsp90α binds to LRP1 to promote MDA-MB-231 cell invasion in vitro and tumour formation in nude mice." (PMID 26846992, 2016). "NT4 selectively targets tumor cells by binding to membrane sulfated glycosaminoglycans (GAG) and to endocytic receptors, like LRP1 and LRP6, which are established tumor markers." (PMID 26626158, 2015). "Recently, it was shown that LRP1 binds to CD44 and thus regulates the adhesive properties of tumor cells." (PMID 26103567, 2015). "LRP-1-mediated activation of FAK, Erk1/2 and Akt pathways can induce tumor cell proliferation, migration and invasion directly or indirectly through MMP-2 and MMP-9 induction." (PMID 25514242, 2014). "Univariate analysis revealed that tumor size, tumor number, microvascular invasion, TNM staging and LRP1 expression were predictors for OS and cumulative recurrence." (PMID 22427881, 2012).
tumor (continued). "Thus, LRP1 may be an especially attractive target for selective receptor-mediated drug delivery to tumours because of the specific microenvironment created by the tumour itself." (PMID 22027709, 2011). "A finding supported by biochemical methodology and the dual expression of LRP1 and P-EphA2S897 in primary and recurrent GBM tumor specimens." (PMID 21408136, 2011). "Through a short-hairpin RNA-mediated silencing approach, we identified LRP-1 as a main regulator of ERK and JNK signaling in a tumor cell context." (PMID 20644732, 2010). "MDK seems to be involved in tumor cell communication through binding several of its receptors, including syndecan 1 (SDC1), SDC4, NCL, and LRP1, and MDK from tumors seems to bind to NCL on macrophages and lymphocytes, though the functional consequences have not been explored." (PMID 40429950, 2025). "In breast cancer with leptomeningeal metastases, circulating tumor cells in the cerebrospinal fluid (CSF) were found to have elevated MDK, which could interact with circulating macrophages and monocytes via the LRP1 or SORL1 receptors." (PMID 40429950, 2025). "In NSCLC, A2M expression was decreased in tumor cells compared to non-malignant lung tissue, while its receptor LRP1 was upregulated in the tumor stroma, indicating a potential compensatory mechanism." (PMID 40649877, 2025). "Additionally, SERPINE1 binds to lipoprotein receptor-related protein 1 (LRP1) via a paracrine mechanism, inhibiting CD8+ T cell infiltration and function in the tumor microenvironment (TME) and promoting M2 macrophage polarization." (PMID 41000398, 2025). "Specifically, glucocorticoids disrupt the balance between the “eat me” signal receptor, low-density lipoprotein receptor-related protein-1 (LRP1), and the “don’t eat me” signal receptor SIRP-α in macrophages, thereby hindering the effective clearance of tumor cells." (PMID 40725081, 2025). "Modulating LRP1 activity could potentially reprogram the TME, sensitising tumours to immunotherapy and improving treatment outcomes." (PMID 39063239, 2024). "Moreover, immunoblot and immunohistochemistry (IHC) staining revealed that LRP1 and Ki67 levels were clearly decreased and increased, respectively, in HCC tissues compared to those in paired adjacent non‐tumor tissues in 30 HCC cases." (PMID 39405202, 2024). "Formation of the Annexin A6/LDL receptor-related protein 1/thrombospondin 1 (ANXA6, SE = 3.9/LRP1, SE = 2.5/THBS1, SE = 6.8) complex was restricted to CAFs and required physio-pathologic culture conditions that improved tumor cell survival and migration." (PMID 38892190, 2024). "Additionally, a pan-cancer analysis demonstrated dysregulated expression patterns of SIRT6, LRP1, and FASN across multiple tumor types." (PMID 39071712, 2024). "In summary, the data highlight the importance of these IRGs in both promoting and preventing tumour progression by indicating a strong correlation between the expression level of genes such as LRP1, PI3, PAEP, FOS, FGF7, and PDGFRA and the degree of tumour immune infiltration in OC." (PMID 39063239, 2024). "Both immunoblot and IHC staining revealed that LRP1 levels were clearly decreased in HCC tissues, accompanied by increased O‐GlcNAcylation levels and reduced OGA levels when compared with those in paired adjacent non‐tumor tissues." (PMID 39405202, 2024). "For all the genotypes, except the Npc1b RNAi negative control, we observed a significant decrease in tumor frequency, showing that not only uptake (LRP1, LpR2) but also intracellular metabolism (Npc1a, CG8112) of cholesterol is necessary for tumor formation itself." (PMID 38893271, 2024).
tumor (continued). "The MDK/LRP1, MDK/ALK, GAS6/MERTK, and GAS6/AXL were identified as potential ligand-receptor pairs involved in the interactions between fibroblasts/endothelial cells and tumor cells." (PMID 37733241, 2023). "Notably, MDK/LRP1, MDK/ALK, GAS6/MERTK, and GAS6/AXL between fibroblasts and tumor cells exhibited a higher communication possibility than that between fibroblasts and thyrocytes." (PMID 37733241, 2023). "PAI-1 binds to a variety of protein, such as PA, VTN and LRP1 by changing conformation states, and most of the PAI-1 complex could promote tumor metastasis 11,13,18." (PMID 36605486, 2023). "The LRP-1 inhibitor, namely RAP, showed an appreciable anti-tumor effect in-vitro." (PMID 36267880, 2022). "Of note, we demonstrate that the tumor growth-promoting activity of this protein lies not in its enzymatic activity but in its ability to act as a ligand for the cell surface receptor LRP1." (PMID 36575174, 2022). "Majority of the GBMs (82.4%) showed strong immunoreactivity for LRP-1, and all tumor cases were positive while the normal brain was negative." (PMID 36267880, 2022). "Here we showed that calpain inhibition in LRP-1-silenced cells restored the mesenchymal morphology of spread FTC133 cells, suggesting that baseline calpain activity maintained through LRP-1-mediated signals contributed to polarize tumor cells." (PMID 36052226, 2022). "The present study evaluated the expression of Cholesterol transporter [importer -Lipoprotein Receptor-related Protein-1 (LRP-1) and exporter -ATP-binding cassette transporters-1 (ABCA-1)] in GBM and their implications in tumor-biology, clinical outcome and therapeutic potentials." (PMID 36267880, 2022). "Recent studies suggest that elevated PAI-1 and LRP1 expression are indicators of poor prognosis for patients with various cancers; however, few studies have distinguished between the expression levels of PAI-1 by cancer nests and tumor stroma." (PMID 33311557, 2021). "To determine LRP-1’s exact role in the in vivo TNBC progression, we performed mammary fat pad experiments by injecting shLRP-1 or shCtrl MDA-MB-231 cells orthotopically into nude mice and followed the tumor development for 28 days." (PMID 34680548, 2021). "Nuclear PXN enhanced tumor angiogenesis by increasing tPA expression, resulting in LRP1-mediated NF-κB activation, a process involving the nonreceptor tyrosine kinase protein SRC." (PMID 33669052, 2021). "ACSL5 is spatially variable in tissue section 1.2 (highly expressed mainly in the tumor), while LRP1 is not (erratically expressed across the entire section)." (PMID 32103057, 2020). "For example, EGF-mediated downregulation of Lrp1 activity in astrocytic tumors impacts ECM composition and may contribute to tumor invasiveness." (PMID 30931303, 2019). "Silencing of LRP1 leads to an increase in the magnitude of ligand-induced conformational change with CXCR3-A focalized at the cell membrane, leading to a sustained receptor activity and an increase in tumor cell migration." (PMID 29146996, 2017). "Our study defines LRP1 as a regulator of CXCR3, which may have important consequences for tumor biology." (PMID 29146996, 2017). "Furthermore, we recently identified LRP-1 as a main endocytic receptor for the hyaluronan receptor CD44, hence fundamentally regulating tumor cell morphology and ECM attachment." (PMID 29108253, 2017). "The level of VEGF is closely associated with microvessel density and the malignant degree of tumors and is increasing in tumor tissues compared with non-tumor tissues, suggesting that VEGF may promote tumorigenesis by regulating LRP1 to enhance angiogenesis." (PMID 26738504, 2016). "In addition to recapitulating known alterations, MutComFocal identifies ARID1B, ROBO2 and MRS1 as candidate tumor suppressors and KLHL6, IL31 and LRP1 as putative oncogenes in DLBCL." (PMID 23531283, 2013).
tumor (continued). "To determine how LRP1 promotes HCC cell migration and invasion, we focused on elucidating the relationship between LRP1 and MMPs which has been reported to participate closely in tumor progression in HCC." (PMID 22427881, 2012). "The present study demonstrates that low expression of LRP1 is a major contributor to the invasion-prone phenotype of HCC, and inhibition of LRP1, coupled to the increased expression and bioactivity of MMP9, enhances tumor cell migration and invasion." (PMID 22427881, 2012). "Conversely, LRP1 expression and endocytosis rates for ANG1005 and Angiopep-2 increased in U87 cells under conditions that mimicked the microenvironment near aggressive tumours, that is, hypoxic and acidic conditions." (PMID 22027709, 2011). "Although the mechanistic basis of its tumor-promoting function is not well defined, eHsp90 elicits pro-motility and pro-invasive behavior, in concert with LRP1, a multi-functional receptor activated by a diverse set of ligands." (PMID 21408136, 2011). "It therefore appears that the mechanisms by which LRP-1 controls tumor progression are not solely related to its endocytic function." (PMID 20644732, 2010). "Coimmunoprecipitation experiments were performed to test whether the intracellular domain of LRP-1 is able to recruit targets involved in the regulation of ERK and JNK signaling pathways in a tumor cell context." (PMID 20644732, 2010). "Low-density lipoprotein receptor-related protein-1 (LRP-1), also known as a cluster of differentiation 91 (CD91), a type I transmembrane protein belonging to the low-density lipoprotein receptor (LDL-R) family, is expressed in many cell types, such as hepatocytes and tumor cells." (PMID 40214585, 2025). "Additionally, the ssGSEA algorithm revealed a significant negative effect of LRP1-expressing CAFs on patient survival, further indicating that LRP1 expression was correlated with the generation of pro-tumor fibroblasts." (PMID 37153545, 2023). "Interestingly, MMP-2 and MMP-9 can bind to low-density lipoprotein receptor-related protein 1 (LRP1), activate ERK, inhibit the JNK pathway, facilitate tight adhesion of tumor cells to the stroma, and induce tumor cell invasion into blood vessels and lymphatic vessels." (PMID 37359527, 2023). "Therefore, blocking the binding of LRP1 and PAI-1 can indirectly inhibit tumor metastasis." (PMID 36605486, 2023). "Although a similar trend could be observed in LRP-1 expressing control tumor cells, it was not significant." (PMID 36052226, 2022). "In comparison to LRP-1 down-regulation, neither Hsp90α-KO, α-KO-#1 cell, nor anti-Hsp90α neutralizing antibody, mAb1G6-D7, was able to achieve a complete inhibition of the self-supported motility of the tumour cells." (PMID 35835845, 2022). "Thus, LRP1 mRNA expression levels on whole tumor samples is more likely to reflect stromal cell expression rather than being representative of tumor cell expression." (PMID 29507659, 2018). "Moreover, LRP1 mRNA expression levels and LRP1 IHC score in tumor cells were neither correlated with LRP1 intronic or promoter levels nor with global methylation as evaluated by LINE1 methylation levels." (PMID 29507659, 2018). "Moreover, linear regression analyses revealed that miR-205 tended to stimulate LRP1 mRNA expression (p = 0.06; R2 = 0.10) despite the absence of correlation with LRP1 IHC score in tumor cells." (PMID 29507659, 2018). "The reverse is true for MDA-MB-468 that lacks LRP1, showed poor invasion and could not form tumours in nude mice." (PMID 26846992, 2016). "However, there seems little doubt that CD91/LRP1 is a bona fide HSP receptor, and this protein appears to play key roles in, for instance, responses to Hsp90α in the wound healing response and in tumor metastasis." (PMID 27199984, 2016). "Also the importance of LRP1 expression in non-tumor cells in the tumor environment has been demonstrated." (PMID 26617523, 2015).